GDF15 (growth differentiation factor 15)
Diseases named in the same sentence as GDF15 in open-access papers (continued):
Sharing a sentence is not in itself a finding about the gene and the disease.
neurological diseases (4 papers, 2017 to 2025). "Using a very heterogeneous cohort of 530 consecutive ICU patients including neurological disorders and post-surgery patients, Dieplinger and coworkers suggested high GDF-15 levels as an indicator of increased mortality risk." (PMID 29180833, 2017). "This knowledge is important for a potential and clinical role of GDF15 as a mediator of the fat-brain axis in metabolic and neurological diseases." (PMID 40820083, 2025). "Data on a role of GDF15 in neurological diseases are diverse, partially contradictive and difficult to interpret." (PMID 40820083, 2025). "Little is known about adipocytic regulation of GDF15, its concentrations in serum and cerebrospinal fluid (CSF), its permeability to the brain, and its correlation with neurological diseases." (PMID 40820083, 2025). "One of the main advantages of the present study is the presentation of reliable GDF15 serum and CSF concentrations in a large cohort of deeply characterized controls and patients with neurological diseases." (PMID 40820083, 2025). "We aimed to investigate a large and deeply characterized cohort of patients undergoing neurological evaluation including spinal puncture in order to test GDF15 concentrations for a potential role as a biomarker in several neurological diseases." (PMID 40820083, 2025). "In this analysis, we aimed to quantitative analysis the levels of GDF15 in patients with neurological diseases and in health control, and then to determine its potential diagnostic utility." (PMID 35068064, 2022). "It was the aim to investigate whether GDF15 in CSF might represent a potential biomarker for neurological diseases or a candidate for a pathophysiologic role in neurologic disorders." (PMID 40820083, 2025). "Therefore, we aimed to quantitative analysis the levels of GDF15 in patients with neurological diseases and in health control, and then to determine its potential diagnostic utility." (PMID 35068064, 2022).
peripheral neuropathy (4 papers, 2020 to 2025). A disorder affecting the peripheral nervous system. "Collectively, our study results reveal a significant association between serum GDF15 and peripheral neuropathy, as defined by NCV in subjects with T2DM." (PMID 35683420, 2022). "This novel study demonstrates the association between the serum GDF15 level and peripheral neuropathy, as determined by a nerve conductive study." (PMID 35683420, 2022). "With regards to diabetic peripheral neuropathy (DPN), a previous study identified a higher serum GDF15 level in T1DM with peripheral neuropathy, which was defined by symptoms reported by a patient with abnormal touch sensation." (PMID 35683420, 2022). "The novel observation derived from the current research is that a higher concentration of GDF-15 was observed within the group with peripheral neuropathy vs. patients free from peripheral neuropathy." (PMID 31936869, 2020).
benign tumors (3 papers, 2020 to 2023). "The GDF-15 expression was exceedingly higher in malignant compared to the benign tumors and the control tissue with a significant fold change between FTC and FTA." (PMID 37905271, 2023).
colonic polyps (3 papers, 2015 to 2024). "Apc mutant mice loose NSAID induced protection from the development of colonic polyps if they are germline Gdf15 gene deleted." (PMID 32502202, 2020). "For example, there is a continuing rise in MIC-1/GDF15 serum levels with progression to colonic polyps, high grade dysplastic polyps, localized colorectal cancer (CRC) and then disseminated CRC." (PMID 25695521, 2015). "Serum levels of GDF15 progressively rise with the evolution of colonic polyps to colorectal cancer." (PMID 32502202, 2020).
digestive system tumors (3 papers, 2017 to 2025). "Previous studies have highlighted cytokine growth differentiation factor 15 (GDF-15) as a potential biomarker for digestive system tumors (DST)." (PMID 30808336, 2019).
infectious disease (3 papers, 2023 to 2025). A disorder directly resulting from the presence and activity of a microbial, viral, or parasitic agent in humans. "Growth differentiation factor 15 (GDF15) has been linked to critical illnesses, particularly cardiovascular and infectious diseases, but its dynamic patterns and prognostic value in critically ill patients remain unclear." (PMID 41211323, 2025). "Among five subsets of neurological diagnoses, GDF15 is exclusively increased in CSF and serum of patients with infectious diseases." (PMID 40820083, 2025). "Among five subsets of neurological diagnoses, GDF15 is specifically increased in CSF and serum of patients with infectious diseases." (PMID 40820083, 2025). "The significance of higher GDF15 concentrations in CSF of patients with infectious diseases compared to matched controls remained preserved." (PMID 40820083, 2025). "This phenomenon can be partially explained by the regulatory role of GDF-15 in modulating the immune response of the host to various infectious and non-infectious diseases." (PMID 37446186, 2023). "GDF15 represents a promising adipokine and mediator of the fat-brain-axis that is co-regulated with metabolic factors and elevated in neurological patients with infectious diseases." (PMID 40820083, 2025). "GDF15 represents a promising adipokine and mediator of the fat-brain-axis that is co-regulated with metabolic factors and elevated in neurological patients suffering from infectious diseases." (PMID 40820083, 2025). "Taken together, GDF15 levels in CSF (but not in serum) seem to correlate specifically with infectious diseases of the central nervous system." (PMID 40820083, 2025). "GDF15 concentrations in serum were not correlated to infectious diseases but only to vascular diseases." (PMID 40820083, 2025).
psychiatric disorder (3 papers, 2022 to 2025). A disorder characterized by behavioral and/or psychological abnormalities, often accompanied by physical symptoms. "Assessment of 772 traits across 6610 participants in FINRISK identified associations of GDF15 concentration with a range of phenotypes including all-cause mortality, cardiometabolic disease, respiratory diseases and psychiatric disorders, as well as inflammatory markers." (PMID 35916366, 2022).
genetic diseases (2 papers, 2016 to 2023). "Consistently, clinical experiments have also demonstrated that FGF21 and growth differentiation factor 15 (GDF15) are potential markers of mitochondrial dysfunction, muscle dysplasia, and genetic disorders deficient in oxidative phosphorylation." (PMID 38069273, 2023). "Our results indicate that GDF-15 is a sensitive and specific biomarker to guide the diagnosis of this group of complex genetic diseases." (PMID 26867126, 2016).
digestive diseases (1 paper, 2025). "Notably, leptin (LEP), GDF15, and ADM showed the strongest associations with lung function, while BST2, THBS2, and CEACAM1 exhibited the most significant associations with digestive diseases." (PMID 40048323, 2025).
neurodevelopmental disorder (1 paper, 2024). A behavioral and cognitive disorder with onset during the developmental period that involves impaired or aberrant development of intellectual, motor, or social functions. "More detailed analyses are required to elucidate the mechanisms of GDF-15 in neurodevelopmental disorders." (PMID 39329976, 2024).
GDF15 also shares sentences with these, for which no sentence is quoted: acute myocardial infarction (22 papers); hyperlipidemia (8); polycystic ovary syndrome (7); hypertrophy (6); Mitochondrial Dysfunction (5); head and neck squamous cell carcinoma (4); malignant glioma (4); nonischemic cardiomyopathy (4); thyroid tumor (4); adenocarcinoma (3); Arrhythmia (3); cardioembolic stroke (3); chronic hepatitis C (3); essential hypertension (3); follicular adenoma (3); idiopathic membranous nephropathy (3); inflammatory bowel disease (3); Leigh syndrome (3); leiomyoma (3); morbid obesity (3); papillary thyroid cancer (3); primary biliary cholangitis (3); acute myeloid leukemia (2); alcohol abuse (2); alcoholic liver diseases (2); alcoholic steatohepatitis (2); anti-phospholipid syndrome (2); aortic valve disease (2); Ataxia (2); bipolar disorder (2).
A further 166 diseases each share a sentence with GDF15 in 2 papers or fewer.